ALB (albumin)
Diseases named in the same sentence as ALB in open-access papers (continued):
Sharing a sentence is not in itself a finding about the gene and the disease.
COVID-19 (continued). "Within 30 days after hospital admission, 88.9% of COVID-19 patients were discharged home when on-admission albumin levels were ≥4 g/dL." (PMID 35160039, 2022). "In comparison to the alive group, the deceased had a lower albumin level (37 ± 4.9 vs. 34.4 ± 5.4, p = 0.04) and a higher red blood cell distribution width (13.8 ± 1.4 vs. 14.6 ± 1.9, p = 0.03) during the COVID-19 admission." (PMID 35407640, 2022). "Serum DPP4 activity significantly correlated with clinically meaningful parameters in COVID-19, including the patients' ages, absolute lymphocyte count and serum albumin, C-reactive protein, IL-6 and plasma D-dimer levels." (PMID 35195023, 2022). "Another readily measurable serum parameter reported to be related to the disease severity of COVID-19 is albumin, which is the predominant serum protein that usually serves as an indicator of an individual’s nutritional status." (PMID 35885582, 2022). "Although the fibrinogen-to-albumin ratio (F/R ratio) has been used as an inflammation marker to predict clinical outcomes in patients with cardiovascular diseases, its association with the prognosis of patients with coronavirus disease 2019 (COVID-19) remains unclear." (PMID 35885582, 2022). "Low serum albumin (SA) correlates with mortality in critically ill patients, including those with COVID-19." (PMID 35645213, 2022). "eGFR (65.2 ± 31.1 vs. 79.7 ± 31.1 ml/min, P < 0.001) and serum albumin (32.9 ± 6.4 vs. 36.8 ± 6.4 g/L, P < 0.001) were lower in COVID-19 patients with hyponatremia." (PMID 36714113, 2022). "Serum albumin is also related to the severity of COVID-19; in fact, patients with the most severe forms of SARS-CoV-2 infection display lower albumin values than patients with the mild-to-moderate disease." (PMID 34683480, 2021). "There is little data examining the correlation between serum albumin levels and COVID-19 disease severity." (PMID 33725003, 2021). "WBC, platelet, neutrophil and lymphocyte counts and albumin were higher in COVID-19 patients than dengue patients." (PMID 34611200, 2021). "Decreased serum albumin is one of the most common laboratory alterations in COVID-19 patients that require hospitalization." (PMID 34683480, 2021). "In our study, we also found low serum albumin levels in patients with severe COVID-19 (3.1 ± 0.2, 4.0 ± 0.3 g/dL, P = 0.000)." (PMID 33350294, 2021). "Partially their observations were consistent with our findings, showing significant increases in ALT, AST, LDH, CRP, and coagulation tests in severe COVID-19 cases and a decrease in albumin, when compared to mild cases of infection." (PMID 34200570, 2021). "Decreased levels of albumin and higher levels of AST were also associated with mortality of COVID-19 patients (p = 0.002 and p = 0.009 respectively)." (PMID 34287285, 2021). "Several studies have described alterations in routine laboratory tests in patients affected by COVID-19, including a decrease in serum albumin concentrations." (PMID 33511503, 2021). "Reports of liver injury have been suggested earlier including elevated transferases and INR, and decreased albumin levels, among patients with COVID-19." (PMID 34017658, 2021). "In particular, and in agreement with recent data, plasma albumin was the biochemical marker most strongly affected by COVID-19 severity, which caught our attention." (PMID 33956870, 2021). "model variables (lymphocyte count and albumin levels) along with C5a levels as predictors of severe COVID-19, showed that only the latter two variables were significant (OR 0.707, 95% CI 0.5817–0.815) and (OR 1.001, 95% CI 1.0002–1.003), respectively." (PMID 34966381, 2021). "Plasma albumin levels at the time of ICU admission have previously been established as a risk marker for AKI and COVID-19 severity." (PMID 34113632, 2021). "Admission serum albumin levels appear to be a predictive biomarker for outcomes in COVID-19 patients." (PMID 33725003, 2021).
COVID-19 (continued). "Other authors have also reported remarkably low levels of hemoglobin and albumin in COVID-19 patients, probably due to the rapid turnover of red blood cells that led to hemoglobin degradation." (PMID 34943434, 2021). "Therapeutic albumin infusions have previously been compared to crystalloid in patients with non-COVID-19-related ARDS." (PMID 34367693, 2021). "His reverse transcriptase-polymerase chain reaction (RT-PCR) was positive for COVID-19, and his cerebrospinal fluid (CSF) analysis revealed albumin-cytologic dissociation." (PMID 33854850, 2021). "In this regard, recent studies have described low serum albumin levels in young COVID-19 patients, along with elevated D-Dimer, LDH and the presence of proteinuria and obesity as predictors of critical disease progression." (PMID 34045530, 2021). "Our results strengthen the current available data on the prognostic value of serum albumin in COVID-19 patients and provide a model to predict in-hospital mortality." (PMID 34367693, 2021). "Previous studies have shown that patients with COVID-19 have lower albumin levels, and low levels of serum albumin are significantly related to disease severity and adverse outcomes in patients with COVID-19." (PMID 34900028, 2021). "Our meta-analysis also revealed reduced ALT and albumin levels in patients with COVID-19 albeit with wide ranges." (PMID 34012016, 2021). "In an observational prospective cohort study, Violi and colleagues observed that albumin supplementation dampened hypercoagulability (measured as a reduction in D-dimer levels) in COVID-19 patients." (PMID 34452459, 2021). "COVID-19 is known to have a specific constellation of laboratory findings including decreased albumin, high CRP, high LDH, lymphopenia, and high ESR." (PMID 33627147, 2021). "In this sense, the CRP-to-albumin ratio better predicts the severity of COVID-19 than CRP or serum albumin separately." (PMID 34683480, 2021). "Albumin, transaminase, brain natriuretic peptide, and troponin levels were similar in COVID-19 and MIS-C patients." (PMID 33627147, 2021). "In COVID-19, the most abundant proteins were both subtypes of immunoglobulin A and mucins, followed by blood plasma proteins, such as albumin, leukocyte proteins, and inflammatory/antiviral response proteins, such as interferon-induced proteins." (PMID 34139362, 2021). "The proportion of patients with an elevated level of ALT and a depleted level of Albumin (ALB) were significantly lower in the COVID-19 suspected group than the confirmed group (5% vs. 50.9%, p=0.000; 10% vs. 35.8%, p=0.030, respectively)." (PMID 34475899, 2021). "A low level of ALB is closely related to poor survival of COVID-19, and asthmatic children show decreased ALB compared with healthy control involved in increased FeNO." (PMID 35069542, 2021). "Food intake is progressively reduced to 0 to 25% of normal requirement in preceding week in patients with critical COVID-19, and albumin replacement therapy is indicated in some patients." (PMID 33832097, 2021). "During the pandemic, it was found that levels of oxidized albumin in the blood of patients with COVID-19 can be a positive predictor of mortality due to the induction of a cytokine storm." (PMID 34638659, 2021). "A study conducted in 144 COVID-19 patients showed that the neutrophil count-to-albumin ratio (NAR) is an independent predictor of mortality with an AUROC of 0.736." (PMID 34683480, 2021). "Decreased levels of albumin and higher levels of AST were also associated with the mortality of COVID-19 patients." (PMID 34287285, 2021). "Conversely, a combination between the values of IL-15 and albumin significantly improved the ability to predict mortality in COVID-19 patients." (PMID 34683480, 2021). "In contrast, a significant reduction in hemoglobin, hematocrit, RBC count, mean corpuscular hemoglobin concentration (MCHC), serum albumin, and lipoproteins were observed in COVID-19 patients." (PMID 34987511, 2021).
COVID-19 (continued). "Consequently, the identification of relatively low serum albumin concentrations in hospitalized COVID-19 patients might assist with appropriate risk stratification and selection of suitable care pathways, even taking into consideration that age can be an important confounding factor." (PMID 33511503, 2021). "Levels of hemoglobin and heme-scavenging proteins (i.e., hemopexin, albumin) were often changed in COVID-19 patients." (PMID 33925394, 2021). "As we have shown here, the IL-15-to-albumin ratio can predict mortality in COVID-19 patients with an AUROC of 0.841, which improves the predictive accuracy of NAR, BAR, and CAR." (PMID 34683480, 2021). "A decreased level of albumin is seen in cases of liver damage and is most likely to be induced by systemic inflammation and adverse drug reactions in critically ill COVID-19 patients." (PMID 34462686, 2021). "Lower levels of hemoglobin and albumin are surrogate markers for the hyper-inflammatory state that drives COVID-19 severity." (PMID 34566957, 2021). "The accuracy of urinary SARS-CoV-2 N levels to identify patients at risk for AKI in COVID-19 was further improved by plasma albumin measurements, also previously reported as a risk marker for AKI and COVID-19 severity." (PMID 34113632, 2021). "Our findings have revealed the risk role of direct bilirubin and mean corpuscular hemoglobin, and the protective role of albumin, white blood cell count, neutrophil count, and lymphocyte count on severe COVID-19 in the European population." (PMID 34122505, 2021). "Although further research is required to investigate the relationship between albumin and COVID-19 disease outcomes, the identification of serum albumin as a marker of COVID-19 severity is biologically and clinically relevant." (PMID 33511503, 2021). "We identified age, dyspnea, anorexia, NLR, PLT, AST, ALB, and CRP as independent risk factors associated with in-hospital mortality of COVID-19." (PMID 34733858, 2021). "As we outlined here, this is the first study showing that combining IL-15 serum values with albumin improves mortality prediction in COVID-19 patients." (PMID 34683480, 2021). "Lastly, this study also substantiates the use of AST, GGT, and albumin as COVID-19 severity markers as well as albumin and direct bilirubin as mortality markers along with raised leucocyte count and tachypnoea." (PMID 34055545, 2021). "Alanine aminotransferase (ALT), aspartate aminotransferase (AST), gamma-glutamyl trans-peptidase (GGT), and alkaline phosphatase (ALP) were significantly elevated in contrast to serum albumin that was reduced in COVID-19 survivors (P ≤0.001)." (PMID 34777873, 2021). "There is expressive evidence of low albumin, other inflammation biomarkers, anorexia and fatigue as common symptoms in patients with COVID-19." (PMID 33261670, 2021). "It is well-fitting that our analyses recognize an association of COVID-19 mortality with FPEI, hypotension, albumin deficiency, and renal comorbidities alike." (PMID 35602191, 2021). "As a result, calcium values adjusted for the albumin concentration were highest in the severe COVID-19 cases." (PMID 34966381, 2021). "For markers of liver function, the levels of alkaline phosphatase (ALP), prealbumin, and albumin (ALB) were significantly lower in severe/critical COVID-19 at 1–2 dpi as compared to mild/moderate COVID-19." (PMID 34103487, 2021). "In a pilot study, we found that early on, abnormalities of the urine, serum albumin and antithrombin III (AT-III) were associated with worse outcomes of COVID-19." (PMID 34300217, 2021). "In this study, we have identified nine factors, including age, dyspnea, anorexia, WBC, NLR, PLT, AST, ALB, and CRP, that were the independent risk factors for COVID-19 fatality." (PMID 34733858, 2021). "In the current study, albumin-adjusted serum free thiol concentrations appeared to be lower in COVID-19 subjects as compared to HCs." (PMID 34943125, 2021).
COVID-19 (continued). "Decreased serum albumin levels (<3.5 g/dL) were found more frequently in COVID-19 patients with thromboembolic events compared to thrombosis-free patients, usually in association with elevated levels of C-reactive protein and D-dimer." (PMID 34441957, 2021). "On the other hand, although normal values of serum albumin, we noticed statistically significant reduction of serum albumin in COVID-19 survivors." (PMID 34777873, 2021). "In conclusion, our systematic review and meta-analysis showed that serum albumin concentrations in COVID-19 patients with high disease severity or poor outcomes are significantly lower when compared to those with milder disease." (PMID 33511503, 2021). "Results from Multivariate Analysis (MV) for COVID-19 related hospitalization in the groups with normal and low albumin levels." (PMID 33930096, 2021). "While COVID-19 patients often exhibit high levels of proinflammatory markers as well as an activation of the complement and the coagulation system, hemoglobin and albumin levels have been reported to be remarkably low." (PMID 33925394, 2021). "As we have outlined here, as far as we know, this is the first study demonstrating that the combined use of the IL-15-to-albumin ratio improves mortality prediction in COVID-19 patients that meet hospitalization criteria." (PMID 34683480, 2021). "The mechanisms through which IL-15 and albumin contribute to mortality in COVID-19 remain to be elucidated." (PMID 34683480, 2021). "The results of our study have demonstrated that serum albumin levels are predictive of adverse outcomes in patients with confirmed COVID-19." (PMID 33725003, 2021). "At the same time, according to the comorbidities of COVID-19 patients, hemodialysis (2.6%) and other corresponding symptomatic support treatments, including transfusion of human albumin, nutrition support and so on, were provided." (PMID 34399679, 2021). "The probability for severe disease (i.e., the COVID-19 score) can be calculated using age, albumin, creatinine, high-sensitivity C-reactive protein (CRP), and lactate dehydrogenase (LDH)." (PMID 34123422, 2021). "Irrespective, it would be important to consider frailty and a low albumin in the assessment of patients with COVID-19." (PMID 34043668, 2021). "Of note is a single-center retrospective study of 115 cases where most of the COVID-19 patients with severe illness demonstrated significantly decreased albumin levels, which was even lower during the progression of the disease." (PMID 34287285, 2021). "Our analysis demonstrated the presence of significantly lower serum albumin concentrations in COVID-19 patients with high disease severity or poor outcome when compared to those with low severity or good outcome." (PMID 33511503, 2021). "In this study, we screened eight severity-associated clinical markers of lactate dehydrogenase, C-reactive protein, albumin, comorbidity, electrolyte disturbance, coagulation function, eosinophil and lymphocyte counts in COVID-19 patients." (PMID 34372792, 2021). "The present study on critically ill COVID-19 patients with moderate to severe ARDS showed a correlation of serum albumin, IL-6, and D-dimer all together at admission to ICU, accompanied by chest CT severity score, as independent predictors of mortality." (PMID 33968298, 2021). "Numerous liver biomarkers abnormalities have been described as being associated with COVID-19 encompassing increased levels of total bilirubin, transaminases, γ-GT, LDH, and low albumin levels." (PMID 32879731, 2020). "In COVID-19 patients, the level of serum albumin is decreased and the body requires more serum albumin." (PMID 33088822, 2020). "Consistent with exudative lesions in the lungs, poor nutritional intake after onset in COVID-19 patients, albumin reduction was more pronounced in severe cases than in mild cases." (PMID 32507110, 2020).
COVID-19 (continued). "In the middle-aged COVID-19 patients without comorbidities in this study, patients with high fever, dyspnea, elevated levels of NLR, LDH and D-dimer, as well as decreased ALB in early stage were more common in severe COVID-19." (PMID 33287826, 2020). "In our study, ALB, OH time and d-dimer were finally selected as predictors for the severity of COVID-19 in elderly patients." (PMID 33170150, 2020). "On the other hand, decreased Lymphocyte count and albumin can predict admission to ICU in patients with COVID-19 with acceptable sensitivity (59.32, 95% CI [49.89–68.27]) and specificity (79.31, 95% CI [72.53–85.07])." (PMID 33363185, 2020). "In conclusion, we demonstrated that ALB, d-dimer and OH time are significant predictors of the severity of COVID-19 in elderly patients." (PMID 33170150, 2020). "The mean albumin level was as low as 35.4 g/L in patients with COVID-19, and it was significantly lower in severe patients." (PMID 32555674, 2020). "Excess ascorbate (as expected in intravenous treatment proposed for COVID-19 management, for example) oxidizes and/or degrades hemoglobin and albumin, as evidenced by UV-vis spectroscopy, gel electrophoresis, and mass spectrometry." (PMID 32471171, 2020). "The results of a univariate analysis showed that the odds of survival for elderly patients with COVID-19 were higher in patients having elevations in lymphocyte count, albumin, creatinine, and blood platelet count." (PMID 33585504, 2020). "In severe COVID-19 patients the weighted mean of albumin was lowered by 11.39 g/liter (95% CI = 10.16-12.63) as compared to general population." (PMID 32983698, 2020). "Upon comparing the LFTs of the severe and non-severe group, our results confirmed that patients with the severe clinical presentation of COVID-19 had lower levels of albumin and higher levels of total bilirubin, ALT, and AST relative to their counterparts." (PMID 33194489, 2020). "The results of both analyses showed that comorbidity, ALB, CRP, and age ≥60 years were the most influential risk factors for severe COVID-19 in these patients." (PMID 33330318, 2020). "Similar to LHQW, these chemical compounds involved a variety of biological processes and pathways to treat COVID-19 by combining with key target proteins IL-6, ALB, and MAPK3, which supported the clinical application with COVID-19." (PMID 32483409, 2020). "Albumin levels were significantly lower in patients with severe COVID-19 (WMD: -4.16 [-5.97, -2.35]; p < 0.001; I2 = 95%)." (PMID 32864250, 2020). "After adjustment of these variables, multivariate regression analysis showed that the serum albumin level and lymphocyte count were independent predictors for critical illness due to COVID-19." (PMID 33521032, 2020). "We named the model COVID-19-American Association for Clinical Chemistry (AACC) (age ≥60 years, ALB, comorbidity, and CRP), and the score ranged from 0 to 5 points." (PMID 33330318, 2020). "Elevated inflammatory markers and abnormal blood chemistries were common among COVID-19 patients with CDI, but the mean albumin value was the only difference compared to COVID-19 controls." (PMID 33260943, 2020). "The effects of thymosin, glucocorticoid, albumin, and immunoglobulin on COVID-19 need to be investigated further, particularly in patients with mild and moderate disease." (PMID 32574322, 2020). "We explored the ability of the PNI and each of its components (serum level of albumin and lymphocyte count) using the area under the ROC curve (AUC) for the prediction of critical illness due to COVID-19." (PMID 33521032, 2020). "Compared with the baseline before infection, HD patients with COVID-19 had lower lymphocytes, albumin and glucose, and higher D-dimer, albumin, phosphorus, lactate dehydrogenase, and CRP." (PMID 32722980, 2020). "Clinicians should be aware of the importance of the albumin level in COVID-19 patients and provide nutritional assessment and support at an early stage to reduce the incidence of critical illness." (PMID 33041508, 2020).